IGFBP7 (insulin like growth factor binding protein 7)
Diseases named in the same sentence as IGFBP7 in open-access papers (continued):
Sharing a sentence is not in itself a finding about the gene and the disease.
tumor (continued). "IGFBP7, which is downregulated in PDAC, functions as a tumor suppressor in various cancers." (PMID 40443651, 2025). "This research suggests that inhibiting CD93 primarily improves vascular function, and targeting the IGFBP7/CD93 pathway could be a safe, durable strategy to enhance tumor vasculature." (PMID 40943530, 2025). "Conversely, exosomes derived from tumor-associated macrophages led to increased expression of TGF-β signaling pathway activators in meningioma cells, specifically TGFBI, SNAI1, MMP2, TGF-β1, TGF-β2, IGFBP7, and LTBP2, leading to tumor cells obtaining a more aggressive phenotype." (PMID 40486962, 2025). "In addition to IGFBP7, the remaining differential genes (SDC2, COL8A1, IFI27, and ALDH1A1) were related to tumor drug resistance in the intersection of drug resistance differential genes." (PMID 40224214, 2025). "IGFBP7 expression is not restricted to the tumor vasculature but can be expressed by tumor cells, as well as stromal cells in the TME." (PMID 39045455, 2024). "Nonetheless, normalization of tumor vasculature has been found to promote a host of favorable alterations to the TME, as we have recently demonstrated in preclinical murine models by disrupting CD93 interaction with IGFBP7/MMRN2." (PMID 38468017, 2024). "The band pattern of IGFBP7 showed an increased band intensity in all examined tumor lysates, independent of stage, compared to the control samples." (PMID 38893148, 2024). "The WB band pattern of IGFBP7 showed an increased band intensity in all examined tumor lysates compared to the control samples, independent of tumor stage." (PMID 38893148, 2024). "When IGFBP7 was expressed by tumor cells, it played a role in promoting malignant mesenchymal cell and EMT-phenotype epithelial cell growth in an anchorage-independent manner, which contrasts with its IGFBP7 tumor inhibition function in ECM." (PMID 37660019, 2023). "Furthermore, CAF in GC has been shown to secrete insulin-like growth factor binding protein 7 (IGFBP7), elevating TAM infiltration level and promoting tumor growth." (PMID 38455361, 2023). "We hypothesize that IGFBP7 may be related to the activation of the TGF-β pathway; TGF-β is often secreted by tumor cells in the tumor microenvironment to reshape the tumor microenvironment and immune response." (PMID 37568781, 2023). "By IHC, they found that IGFBP7 expression was higher in tumours with metastasis than in tumours without metastasis." (PMID 37660019, 2023). "Our DGE analysis of non-responding gene expression areas provides some initial molecular detail and shows an upregulation of genes involved in migration, resistance, immunosuppressive function, inflammation, cancer, and tumor stroma (e.g., H2AFJ, FKBP2, MGP, A2M, and IGFBP7)." (PMID 36115838, 2022). "IGFBP7 is a ligand for CD93, and it is upregulated in tumour endothelial cells." (PMID 36077754, 2022). "Moreover, a CD93-targeting monoclonal antibody (mAb) has been demonstrated to reduce tumor growth and enhance the effects of immunotherapy in pancreatic tumors or melanoma via the CD93/IGFBP7 pathway." (PMID 35812369, 2022). "IGFBP7, similar to IGFBP3, might have a dual role as a tumor suppressor within the IGF/insulin system while simultaneously having tumor-promoting effects through other pathways." (PMID 34606580, 2021). "There were no other statistically significant differences in tumor characteristics depending on IGFBP7 levels." (PMID 34606580, 2021). "Our results demonstrated that there is a robustly positive relationship between IGFBP7 expression level and infiltration of macrophages, DCs, CD4+ T cells and CD8+ T cells, which indicated that IGFBP7 may be involved in regulating tumor immunology in GC." (PMID 33531979, 2021). "Both IGFBP-3 and IGFBP-7 levels were relatively stable between the preoperative and 1-year postoperative samples, regardless of tumor characteristics and treatments." (PMID 33767994, 2021).
tumor (continued). "Furthermore, the pathway activated by the interaction between CD93 and insulin-like growth factor binding protein 7 (IGFBP7), an ECM protein upregulated in tumor blood vessels, contributes to abnormal tumor vasculature." (PMID 34830297, 2021). "Genes related to tumor progression, including matrix metallopeptidase 1 or MMP1, S100 calcium binding protein A2 or S100A2, tetraspanin 8 or TSPAN8, and insulin like growth factor binding protein 7 or IGFBP7 were upregulated in GSM3516665-subgroup 2." (PMID 33170151, 2020). "Expression of the IGFBP7 gene did not diverge significantly between tumors of different types, different stages (including tumor size and lymph node status), and grading." (PMID 32500027, 2020). "Apart from confirming targets, such as ERBB2 and S100A11, which are exclusively upregulated in the tumour epithelial cells, qPCR data confirmed that stromal targets such as SPARC, TIMP1, IGFBP7, COL1A1 were upregulated specifically in stromal components and not in epithelial components." (PMID 31959771, 2020). "Several other tumor vascular targets, such as vascular endothelial growth factor receptor 2 (VEGFR-2), αvβ3 and αvβ5 integrins and insulin-like growth factor binding protein 7 (IGFBP7), have been used to visualize tumor angiogenesis by PET, optical imaging and MRI." (PMID 33353213, 2020). "In preclinical mouse model of glioblastoma, fluorescent-labeled Nbs targeting IGFBP7 have been applied to visualize tumor vasculature by non-invasive optical imaging." (PMID 33353213, 2020). "In conjunction with these data, IHC analysis of the patient tumor revealed that Ki-67-negative, non-cycling cells showed a higher immunoreactivity against IGFBP7, MDK, and B2M." (PMID 32460812, 2020). "Angiomodulin (AGM) also known as IGF binding protein 7 (IGFBP7), is a secreted factor (stored in Weibel-Palade granules) reported to be expressed by developing vasculature in general and to be upregulated by pathological tumor vasculature." (PMID 32238174, 2020). "Unlike IGFBP-1 to IGFBP-6, IGFBP-7 inhibits the proliferation of tumor cells by directly binding IGF1R." (PMID 31661774, 2019). "IGFBP7 expressed by TECs suppresses IGF1R signaling and the stem-cell-like property of tumor cells." (PMID 31600937, 2019). "Among 22 genes with a negative regression coefficient, loss of IGFBP7 expression showed a role in thyroid carcinogenesis, LIMK2 showed a potential role as a tumor suppressor, consistent with this study." (PMID 30729678, 2019). "IGFBPrP1, known as Mac25 or IGFBP7, plays the role of a tumor suppressor." (PMID 29702590, 2018). "IGFBP7 binds the IGF1R and functions as a candidate tumor suppressor." (PMID 29702590, 2018). "Protein expression analysis of HGSC samples revealed that the large majority of tumour cores (72.6%) showed low or absence of IGFBP7 staining and revealed a significant correlation between IGFBP7 protein expression and a prolonged overall survival (p = 0.044)." (PMID 25886299, 2015). "Compared with different AJCC (American Joint Committee on Cancer) stage of tumor, the advance tumor lesions (T4aN2bM0) showed the absence of IGFBP-7 expression." (PMID 25880247, 2015). "This suggests the possibility that IGFBP7 protein levels are indeed low or absent in the vast number of epithelial tumour cells of HGSCs." (PMID 25886299, 2015). "The IGFBP7 expression in TOV81D is interesting as this cell line is not tumourigenic in immunocompromised mouse tumour xenograft models and was derived from a sample from a patient having an unusually prolonged overall survival which was in excess of 7 years." (PMID 25886299, 2015). "The Igfbp7−/− mice are viable, do not show any gross developmental abnormalities, and remained tumor free." (PMID 24505323, 2014). "In contrast, methylation levels of SLIT2, MAL and IGFBP7 in tumor samples were higher when compared with levels in matched non-malignant lung tissues (P<0.0001, P=0.0010 and P<0.0001, respectively)." (PMID 23381221, 2013).
tumor (continued). "IGFBP7, caspase-3, and VEGF expressions in tumor tissue were measured by immunohistochemistry." (PMID 20158915, 2010). "IGFBP7 and caspase-3, VEGF were mainly expressed in the cytoplasm of tumor cells." (PMID 20158915, 2010). "A recent study indicated that IGFBP7 might exhibit angiogenesis-modulating properties, reducing VEGF expression by regulating IGF availability in body fluids and tumor tissues and modulating combination of IGF-I to its receptors." (PMID 20158915, 2010). "Several studies demonstrated that IGFBP7 is overexpressed in tumour blood vessels with little or no expression in normal blood vessels, nor in the non-malignant angiogenic placental tissues." (PMID 20959824, 2010). "SASP-mediated tumor suppressive functions, such as the secretion of interleukin-6 (IL-6), interleukin-8 (IL-8), plasminogen activator inhibitor-1 (PAI-1), and insulin-like growth factor-binding protein 7 (IGFBP7), enhance senescence arrest in in vitro experiments." (PMID 40722797, 2025). "For instance, when ECs undergo chemotherapy, insulin-like growth factor binding protein-7 (IGFBP7/angiomodulin) expression is suppressed, resulting in the emergence of chemoresistant and aggressive tumor cells, which potentially contribute to tumor progression and metastasis." (PMID 37666809, 2023). "Moreover, IGFBP7 expression was downregulated in tumour tissue compared with adjacent nontumour tissue at both the mRNA and protein levels." (PMID 37660019, 2023). "At low magnification (10×), it could be observed that IGFBP7 protein was mainly expressed in the α-SMA+ CAFs, which are present in the stromal area, whereas there was less detectable expression of IGFBP7 in panCK+ tumor cells." (PMID 37568781, 2023). "Exogenous recombinant IGFBP7 treatment on M0 macrophages decreased the expression level of the biomarkers in M1 macrophages with a pro-inflammatory phenotype and increased the expression level of biomarkers in M2/TAM-like macrophages with a pro-tumor phenotype." (PMID 36681667, 2023). "Despite inhibition of IGFBP7 and MDK may be a useful adjunct to co-targeting tumor cells and CAFs in patients with MyoCAF-rich tumors, few targeting agents are currently available for these molecules, which led us to focus on TME that showed immunosuppressive features." (PMID 32460812, 2020). "Furthermore, the relative increase in the transcriptional and translational expression level of insulin-like growth factor-binding protein 7 (IGFBP7), midkine (MDK), and beta-2-microglobulin (B2M) genes was observed in remnant tumor cells after tipifarnib treatment." (PMID 32460812, 2020). "Insulin-like growth factor binding protein 7 (IGFBP7), a gene suspected to play a role in tumour suppressor pathways in various cancer types but not extensively studied in EOC, was among the list of genes which were reprogrammed as a consequence of tumour suppression in our OV90 cell line model." (PMID 25886299, 2015). "Thus, the majority of the tumour samples (72.6%) expressed either absent or low levels of IGFBP7 protein and these results overall are consistent with low levels of gene expression." (PMID 25886299, 2015). "Comparisons of tumor tissue with matched non-malignant lung tissue indicated that aberrant methylation of LINE-1, SLIT2, MAL and IGFBP7 were all tumor-specific events (all P<0.0001), despite the fact that tumor tissues consist of mixtures of tumor cells and non-malignant cells." (PMID 23381221, 2013). "IGFBP7 is highly expressed in the blood vessels of various human cancer tissues, suggesting that it might suppress the pathological action of VEGF, which is mainly derived from tumor cells." (PMID 21197468, 2011). "The inhibitory effect of IGFBP7 on tumorigenicity might be partially mediated by its ability to suppress VEGF-stimulated angiogenesis, although there is so far no direct evidence to explain if IGFBP7 affects tumor blood vessels." (PMID 21197468, 2011).
tumor (continued). "Similarly, the anti-IGFBP7 sdAb-functionalised PEGylated Fe3O4 NP-Cy5.5 demonstrated enhanced tumour signal compared with non-targeted NPs." (PMID 20959824, 2010). "In brain sections of GBM-bearing mice, IGFBP7 immunoreactivity detected by anti-IGFBP7 sdAb (clone 4.43) was enhanced and detected specifically in the tumours, but not in normal brain, and colocalised with the immunoreactivity against the vascular antigen, CD31." (PMID 20959824, 2010). "The SPs from luminal-type BC were analysed for BC T-IC characteristics, including human epidermal growth factor receptor 2 (HER2), ERα, IGFBP7 expression and their ability to initiate tumours in non-obese diabetic severe combined immunodeficiency (NOD/SCID) mice." (PMID 20145614, 2010). "Therefore, IGFBP7 is a selective and abundantly expressed biomarker of human GBM vessels that could be exploited for selective targeting of tumour vessels for imaging and therapeutic applications." (PMID 20959824, 2010). "No IGFBP7 expression was observed in non-tumour brain vessels or in non-vascular cells." (PMID 20959824, 2010). "Moreover, tumor cells lacking IGFBP7 expression could be restored by treatment with the DNA methylation inhibitor 5-aza-2′-deoxycytidine." (PMID 31183073, 2019). "Thus, IGFBP-7 may be an efficacious anticancer agent and related experiments have provided the evidence that IGFBPs possess both IGF-dependent and -independent anti-tumor actions." (PMID 25880247, 2015). "And transcriptional data reveal that compared to the adjacent non-tumorous samples, expression of COL3A1, COL1A2, FBN1, IGFBP7, and FSTL1 was significantly elevated in the tumor tissue." (PMID 38478111, 2024). "Currently, co-targeting of dormant tumor cells and MyoCAFs by therapeutic inhibition of MDK and IGFBP7 is not available." (PMID 32460812, 2020). "Furthermore, in vivo administration of Nor led to a reduction in tumor growth, weight, and secretion of LGALS1 and IGFBP7 in HGC‐27‐formed xenograft models, alongside decreased proliferation index (Ki‐67), reduced CD31‐positive microvessels, and altered levels of AKT phosphorylation and EMT markers." (PMID 40995693, 2025).
cancer (98 papers, 2008 to 2025). A tumor composed of atypical neoplastic, often pleomorphic cells that invade other tissues. "Although IGFBP7 has been identified as a cancer suppressor, in this study it was associated with resistance to three generations of EGFR TKI drugs." (PMID 40224214, 2025). "In conclusion, this study indicated that IGFBP7 has important clinical significance in GC and is associated with immune cell infiltration, such as that of cancer‐related fibroblasts, and the sensitivity to antitumor drugs, such as erlotinib." (PMID 39351597, 2024). "Among these immune cells, the infiltration of cancer‐associated fibroblasts and endothelial cells was most significantly correlated with IGFBP7 expression in both the TCGA‐STAD and GSE29272 datasets." (PMID 39351597, 2024). "In the cancer setting, tumor-associated ECs were found to express IGFBP7 which stimulates IGF1 receptors on cancer cells thereby activating an FGF4 signaling loop that contributes to chemoresistance." (PMID 37060495, 2023). "The evidence showed that the IGFBP2 levels are associated with cancer cell invasion and metastasis; instead, IGFBP7 displays an ambiguous activity as an oncogene or suppressor gene in distinct types of cancers." (PMID 34440012, 2021). "In each of these cancer types or cell lines, IGFBP7 was shown down-regulated and in some cases, loss of heterozygosity (LOH), gene deletion or DNA methylation were postulated as a mechanism of inactivation to affect the gene expression." (PMID 25886299, 2015). "In various cancer types, IGFBP7 has been implicated in cellular processes including cell differentiation, cell adhesion, angiogenesis, cell growth and survival, senescence and apoptosis." (PMID 25886299, 2015). "The data indicated the methylation status of IGFBP-7 was associated with invasive depth, loco-regional recurrence and cancer sequence (p = 0.03, 0.011 and 0.029, respectively)." (PMID 25880247, 2015). "We found that these two CpG sites in the IGFBP7 promoter are cancer-specifically methylated and strongly associated with both BRAFV600E (Wilcoxon rank-sum test, P value = 2.0×10−10) and CIMP (P value = 3.6×10−9)." (PMID 20027224, 2009). "Indeed, IGFBP7 was reported to be highly expressed in the stroma of some tumors and co-localized with activated cancer-associated fibroblasts (CAFs)." (PMID 39045455, 2024). "In addition, IGFBP7 is related to several cancer‐associated pathways, including ECM receptor interaction, focal adhesion, DNA replication and the citrate cycle." (PMID 39351597, 2024). "Moreover, the significant correlation between IGFBP7 expression and cancer‐associated fibroblasts was also verified by the TIDE online tool in both the TCGA‐STAD and GSE29272 datasets." (PMID 39351597, 2024). "Mechanismly, IGFBP7 was highly expressed in cancer-associated fibroblasts (CAF) and mesenchymal cells, and was induced by epithelial-to-mesenchymal transition (EMT) signaling, since its expression was increased by TGF-beta treatment and reduced by overexpression of OVOL2 in GC." (PMID 36681667, 2023). "Relevant to our results, loss of IGFBP7 has been associated with chemo-resistance to cisplatin in human cancer cell lines and lung xenografts, possibly by the extracellular signal-regulated kinase (ERK) mitogen-activated protein kinase (MEK-ERK) pathway regulation." (PMID 35120576, 2022). "Also, the expression of IGFBP3 and IGFBP7 is frequently reduced in several kinds of cancers, and this decrease is usually caused by promoter methylation." (PMID 32500027, 2020). "Tumors with high IGFBP7 gene expression had a microenvironment enriched for stromal cells while deficient in immune cells, characterized by transforming growth factor beta signaling, indicating enrichment of cancer-associated fibroblasts and aging tissue features." (PMID 39362991, 2024). "Interestingly, abnormal expressions of IGFBP6 and IGFBP7 were associated with cancer." (PMID 36831184, 2023).